HIF1A (hypoxia inducible factor 1 subunit alpha)
Diseases named in the same sentence as HIF1A in open-access papers (continued):
Sharing a sentence is not in itself a finding about the gene and the disease.
tumor (continued). "Hypoxic HIF1α-/- T cells are less able to kill tumor cells, and HIF1α-/- tumor-bearing mice are not responsive to immune checkpoint blockade (ICB) therapy, indicating loss of HIF1α in T cells is a major mechanism of therapeutic resistance to ICBs." (PMID 38260594, 2024). "HIF-1α RNAi could downregulate the levels of HIF-1α and VEGF, inhibit tumor angiogenesis, and lessen metastases." (PMID 39204162, 2024). "The NCDS could co-deliver si-HIF1α and GEM into panc-1 cells, thus inhibiting the expression of HIF1α and showing an excellent ability of suppressing tumor metastasis." (PMID 38831883, 2024). "HIF‐1α is recognised to induce the expression of carbonic anhydrase IX (CAIX), an enzyme that has been attributed a central role in pH regulation and cancer progression and is particularly pronounced in peri‐necrotic tumour areas, high‐grade BCs." (PMID 39660488, 2024). "In addition, the regulation of HIF-1α and GSH releases Tregs-induced immunosuppressive binding, thereby completely activating the immune anti-tumor response, providing a new immunomodulatory strategy from the perspective of redox regulation." (PMID 39728157, 2024). "HIF-1α is a transcription factor that stabilizes and activates under hypoxic conditions, promoting VEGF production to form new blood vessels necessary for supplying the tumour with oxygen and nutrients." (PMID 39498386, 2024). "The association of acriflavin, an inhibitor of HIF-1α/HIF-1β dimerization, with PDT with PS 5-aminolevulinic acid (5-ALA-PDT) reduced the expression of HIF-1α, GLUT-1, GLUT-3, and HK2, improved the efficacy of the treatment of refractory GBM, and reduced tumor cell invasion and migration." (PMID 39201395, 2024). "This interaction between HIF-1α and TGF-β creates a favorable TME condition for tumor progression." (PMID 38542288, 2024). "Nine tumor samples (32.14%) with high VEGF showed a concurrent HIF-1α positivity, while seven specimens (25%) were negative to both markers." (PMID 39595235, 2024). ", HIF-1A was significantly expressed in nearly 57% of tumor samples compared to only 5.6% in peritumoral tissues; more importantly, the expression of HIF-1A, not HIF-2A, is positively correlated to cancer cells infiltration and invasion, and metastasis." (PMID 39567394, 2024). "Subsequent genetic evidence, however, indicated that inactivation of Hif1a and/or Hif2a accelerates AML initiation, indicating a tumor-suppressor function for HIFs5,6, thus suggesting that one potential therapeutic strategy for AML is to pharmacologically enhance HIF stability." (PMID 38637657, 2024). "We establish that the lack of oxygen in vivo—hypoxia—counteracts the tumor-suppressive effects of C/EBPδ, and identify a reciprocal feedback loop between C/EBPδ and HIF-1α." (PMID 39273396, 2024). "In a lung cancer mouse model, exposure to additional oxygen (in breathing O2, levels rose from 21% to 60%) demonstrated that exogenous oxygen supplementation can reduce HIF-1α levels along with its downstream proteins, reversing the hypoxic, adenosine-rich TME, thereby promoting tumor regression." (PMID 39421736, 2024). "HIF-1α expression can stimulate VEGF production and promote tumor angiogenesis." (PMID 38713256, 2024). "Immunofluorescence analysis of allograft tumor tissues revealed that BPTES reduced the protein levels of CD80, CD204, hypusinated eIF5A, and HIF-1α, indicating that inhibition of HCC growth can be achieved by targeting eIF5A hypusination in TAMs via regulation of glutamine metabolism." (PMID 38689086, 2024). "Additionally, in the context of tumor microenvironment (TME) acidification, the export of lactate ions and H+ ions through hypoxia/HIF-1α-driven MCT4 enhances the acidity of the TME." (PMID 38625978, 2024).
tumor (continued). "In the case of phototherapy (808 nm, 200 mW cm−2, 1 min), the tumor was smaller, but the protein levels of PD-L1 and HIF-1α did not change significantly compared to the dark application." (PMID 39138299, 2024). "On the other hand, an over-expression of HIF-2α in CD8 T cells, as opposed to HIF-1α, was found to boost the anti-tumor cytotoxicity of CD8 T cells." (PMID 39242595, 2024). "Expression of Hif1a over pseudotime was evident, however, its targeted deletion in NK cells failed to change NK cell fate within the tumor models we assessed." (PMID 38267402, 2024). "Also, elevated HIF-1α expression has been found to be correlated with clinicopathological characteristics, poor survival in HCC patients, and tumor immune cell infiltration." (PMID 39466438, 2024). "Moreover, previous studies in tumor cells have demonstrated that dimeric PKM2 complexed with b-catenin, STAT3, Oct4, NF-kB/p65, and HIF-1a to regulate the expression of target genes." (PMID 38483700, 2024). "Further, WB results exhibited that curcumin was able to inhibit HIF-1α and PD-L1 expression in the inflammatory environment established by LPS-stimulated CT26 cells, suggesting that curcumin suppressed tumor immune escape by inhibiting the TLR4/HIF-1α/PD-L1 pathway." (PMID 38612546, 2024). "Similar results were observed in the tumour tissues of mice treated with anlotinib alone or in combination with anti‐PD‐1 (all p‐values < 0.05), indicating that anlotinib inhibits TFRC through inactivation of the VEGFR2/AKT/HIF‐1α axis." (PMID 39095323, 2024). "Additionally, HIF-1α upregulation, triggered by IFN-γ in MSCs, acts as a key mediator of increased VEGF expression, leading to enhanced tumor angiogenesis." (PMID 39450177, 2024). "Other studies have shown that irradiation (IR) can upregulate HIF-1α/VEGF, modestly compared to hypoxia-induced expression, signifying a secondary silent tumor repair activity, despite its successful treatment, as indicated by the decreased 18F-FLT PET uptake and the increased γH2AX." (PMID 39055895, 2024). "HIF-1α also regulates genes involved in cell survival and metabolism, such as phosphoglycerate kinase (PGK), carbonic anhydrase 9 (CA9), Bcl-2 interacting protein 3 (BNIP3), and glucose transporter 1 (GLUT1), all of which contribute to tumor progression." (PMID 38339244, 2024). "By focusing on the HIF1α-SMURF2 axis, researchers and clinicians could develop innovative strategies to combat tumor progression, improve treatment responses, and potentially overcome resistance in cancer therapy." (PMID 39697237, 2024). "Recent reports have demonstrated that miR-138-5p exerts a repressive effect on the proliferation of endothelial progenitor cells by inhibiting hypoxia-inducible factor-1α (HIF-1α) and vascular endothelial growth factor A (VEGFA), both master regulators of angiogenesis and tumor vascular mimicry." (PMID 39596302, 2024). "In addition, the signaling pathway involving HIF-1α, its downstream factor VEGFA, and its receptor VEGFR has received considerable attention for its role in promoting tumor growth and metastasis." (PMID 39149033, 2024). "HIF1A expression was increased in surrounding areas of the tumor, although not where the hypoxic signature was highest." (PMID 38758780, 2024). "Therefore, we measured the tumor HIF-1α, lactate dehydrogenase and lactic acid concentrations to evaluate the effect of USMC on tumor glycolytic metabolism." (PMID 39091919, 2024). "Since it has been demonstrated that HIF-1α is overexpressed in a number of different forms of cancer, including CRC, the inhibition of HIF-1α is currently at the forefront of the list of targets for anti-tumor therapy." (PMID 39031216, 2024). "HIF-1α expression is frequently absent during tumor progression, and sequencing data are consistent with clinical data, suggesting that HIF-1α helps inhibit tumor growth." (PMID 38419050, 2024).
tumor (continued). "Both C/EBPδ and HIF-1α might thus contribute to the reduced suppression of MYC targets upon C/EBPδ induction under hypoxia and promote tumor cell survival in vivo." (PMID 39273396, 2024). "Furthermore, elevated levels of HIF‐1α and GLUT‐1, induced by tumor hypoxia and inflammation, often mediate tumor progression and further enhance PD‐L1 expression." (PMID 39162005, 2024). "Since ETAR receptor activation induces VEGF expression via HIF-1α and VEGF drives angiogenesis, one could speculate that elevated VEGF levels in this particular patient subset enabled tumor vascularization to rapidly drive cancer growth." (PMID 38785410, 2024). "In the 3-methylcholanthrene induced tumor mouse model, a gold‐manganese oxide nanocomposite induced hypoxia in the tumor microenvironment, and the level of pro-inflammatory cytokines: TNF-α, IL-10, and HIF-1α were decreased." (PMID 38082190, 2024). "In addition to tumorigenesis, MYC also facilitates serine/glycine biosynthesis, along with HIF-1α and ATF4, which can integrate the anaerobic glucose metabolic cycle in tumor cells." (PMID 37450923, 2024). "Isolated from Sorbariasorbifolia, TTF1, also known as 5,2′,4′-Trihydroxy-6,7,5′-trimethoxyflavone, has showcased its capacity to inhibit tumor angiogenesis elicited by HepG-2 cells via reducing the VEGF, KDR, bFGF, COX-2, and HIF-1α levels of RNA and protein in key factors regulating angiogenesis." (PMID 38611849, 2024). "Additionally, hypoxia activates HIF1α via the IL-6/STAT3 signaling pathway, resulting in increased CD133 expression and the maintenance of tumor cell stemness." (PMID 38230205, 2024). "In clear cell renal cell carcinoma (ccRCC) and TNBC, hypoxia and HIF-1α play a pivotal role in amplifying the metastatic potential of tumor cells through non-canonical functions and enhanced EZH2 phosphorylation." (PMID 38911968, 2024). "Hypoxic Hif1α–/– T cells are less able to kill tumor cells in vitro, and tumor-bearing Hif1α–/– mice are not responsive to immune checkpoint blockade (ICB) therapy in vivo." (PMID 39477954, 2024). "Moreover, HIF-1α augments autophagy by modulating the expression of BNIP3, a protein central to stress adaptation mechanisms that fortify tumor cell survival while sidestepping apoptosis." (PMID 38240686, 2024). "Explicitly, targeting HIF-1α or its downstream regulatory pathways (e.g., CXCL12/CXCR4 axis) at the tumor and stromal cell levels may be a viable strategy to surmount HME-mediated protection of CLL cells." (PMID 37588219, 2024). "Previously, we identified that tumor-suppressive miR-99b-5p is frequently downregulated in aggressive African American (AA) PCa and European American (EA) CRPC, leading to upregulation of mTOR, androgen receptor (AR), and HIF-1α signaling." (PMID 38792011, 2024). "Hypoxia significantly up‐regulates PD‐L1 in macrophages, DCs and tumour cells, with the up‐regulation depending on HIF‐1α, not HIF‐2α." (PMID 38935536, 2024). "The activity of HIF-1α, rather antitumorigenic in this specific cancer, is strongly decreased due to chromosomal deletions or HAF activity leaving HIF-2 to fully exert its pro-tumor activity." (PMID 39048564, 2024). "The intricate network of TFs, including SOX2, OCT4, NANOG, KLF4, c-MYC,β-catenin, STAT3, NF-κB, HIF-1α and YAP/TAZ, is central to the maintenance of the stem-likeproperties of GSCs, which in turn drive tumor heterogeneity, therapeutic resistance, andrecurrence." (PMID 38716541, 2024). "Under normal conditions, prolyl hydroxylase (PHD) targets HIF-1α for degradation; however, reduced PHD activity in tumors stabilizes HIF-1α, resulting in its accumulation and the subsequent promotion of glycolysis to support tumor growth." (PMID 39596452, 2024). "The pro-angiogenic activity of HIF-1α is not restricted to endothelial cells, as it also affects the behavior of other cell types, including tumor and inflammatory/immune cells." (PMID 38725568, 2024).
tumor (continued). "HIF-1α also stimulates proteolytic enzymes such as matrix metalloproteinase (MMP), collagenase, and fibronectin to remodel the extracellular matrix (ECM) for tumor survival." (PMID 38542288, 2024). "The strong anti-tumor ability of the MIL-101/ACF@CCM group was hypothesized to be attributed to the increased production of ROS and the inhibition of HIF-1α expression through the release of ACF." (PMID 38794281, 2024). "Hypoxia-inducible factor 1 alpha (HIF1α), a transcription factor that regulates the cellular response to hypoxia and is upregulated in HCC, plays a crucial role in growth, metastasis, tumor angiogenesis, and therapy resistance." (PMID 39420007, 2024). "HIF-1α facilitates ubiquitination and proteolysis of the E1 subunit of the OGDH complex, an outcome in accordance with the OGDH-E1 variation determined in this study on the surface of the tumor." (PMID 39195201, 2024). "This indicates a tumor-biological positive effect of reduced GLUT-1 and HIF-1α expressions." (PMID 38474362, 2024). "The activation of genes such as VEGFA and VEGFR1 under hypoxic conditions underscores the potential of HIF1α and VEGF as biomarkers for aggressive cancer phenotypes, indicating tumor aggressiveness and metastatic potential, which is valuable for prognosis and treatment planning." (PMID 39697237, 2024). "The analysis of HIF-1α alone showed a more significant correlation with certain prognostic features of CRC than when HIF-1α was analyzed on the basis of VEGF and IL-33 expressions in tumor cells." (PMID 38313904, 2024). "However, in human SCC, HIF1α expression is higher in late-stage SCC lesions compared to normal skin and preneoplastic lesions, and it is not known how Kin1−/− tumors may utilize a hypoxic environment to promote tumor growth, although we did observe changes associated with glycolytic metabolism." (PMID 38982038, 2024). "We observed a higher DNA methylation level of the HIF1A promoter region in normal tissues compared to tumors (p = 0.002) and, on the contrary, higher DNA methylation in promoter regions of EGLN2 and EGLN3 (p = 0.04 and p < 0.0001) in HNSCC tumor tissues." (PMID 38928200, 2024). "Tumor cells promote CAF generation, and the CAFs, in turn, improve the invasiveness and metastasis of the malignant T cells through the IL-6/JAK2/STAT3/SOX4 or IL-6/HIF-1α/SOX4 pathway." (PMID 39963655, 2024). "These treatment strategies may involve targeting glucose supply, which can have toxic effects on tumor cells in the hypoxic TME, or inhibiting key enzymes in the glycolytic pathway, including glucose transporters, HIF-1α, and the mTOR pathway." (PMID 39227970, 2024). "Notably, the Wnt signaling pathway can promote intracellular glycolysis by activating HIF-1α, Glut1, HK, and PKM2 in tumor cells." (PMID 38448948, 2024). "We found significantly higher mRNA levels of EGLN3, HIF1A, GLUT1, VEGF, and CA9 (p = 0.021; p < 0.0001; p < 0.0001; p = 0.004, and p < 0.0001, respectively) genes in tumor tissues compared to normal ones and downregulation of the EGLN1 mRNA level in tumor tissues (p = 0.0013)." (PMID 38928200, 2024). "Under hypoxic conditions, tumor cells adapt to environmental stress and facilitate cell proliferation and metastasis through the activation of various HIF signaling pathways, including HIF-1α and HIF-2α." (PMID 39590319, 2024). "Synergy with hypoxia-inducible factor 1-alpha targeting: Reducing HIF-1α expression could promote TIL function and survival in the context of hypoxia within the tumor microenvironment." (PMID 39493156, 2024). "Elevated levels of HIF-1α confer radioresistance through various pro-cancer mechanisms, including cell cycle arrest, altered energy metabolism, autophagy, epithelial-mesenchymal transition (EMT), apoptosis, DDR, and modulation of tumor immunity." (PMID 39655194, 2024).
tumor (continued). "Since HIF-1α activation promotes the migration of Tregs to the TME, specific knockout of HIF-1α in Tregs has been reported to reduce the proportion of TI-Tregs and limit tumor development." (PMID 38644503, 2024). "In fact, GPx2 KD tumours showed HIF1α upregulation that was accompanied by increased SNAI1, TWIST, N-CAD and decreased E-CAD expression, thus supporting effects of HIF1α on EMT." (PMID 38238426, 2024). "Additionally, in human breast cancer, stable HIF-1α induced by LSD1 interacts synergistically with CBP and MTA1 to promote tumor angiogenesis induced by VEGF, providing continuous oxygen and nutrition for tumor growth." (PMID 39629133, 2024). "Specifically, hypoxia is known to activate inducible factors, such as hypoxia-inducible factor 1alpha (HIF-1α), which in turn can stimulate tumor neo-angiogenesis through activation of various downward mediators, such as the vascular endothelial growth factor (VEGF)." (PMID 39055895, 2024). "Thus, the hyperexpression of HIF-1α in GBM leads to the hyperexpression of FAT, FABPpm, FATP, and, secondarily, the increase in the absorption of FAs and the formation of LDs in the tumor microenvironment." (PMID 38791520, 2024). "Finally, JHU083 caused a global shutdown in glutamine-utilizing metabolic pathways in tumor cells, leading to reduced HIF-1α, c-MYC phosphorylation, and induction of tumor cell apoptosis, all key antitumor features." (PMID 38701369, 2024). "Meanwhile, inhibition of miR-664a-3p could significantly decrease the expression of HIF-1α, VEGFA, and VEGFC, which have been reported to act as factors that contribute to tumour angiogenesis." (PMID 38035445, 2024). "The expression of HIF-1α, HPRT1 and Ki67 in mouse tumor tissues was detected by IHC." (PMID 39343971, 2024). "Additionally, HIF-1α facilitates the synthesis of vascular endothelial growth factor (VEGF), which in turn stimulates tumor angiogenesis and consequently accelerates cancer progression." (PMID 39590319, 2024). "While combo ICB potently suppressed tumor growth in WT mice, it failed to do so in Hif1α− / − mice, revealing T cell-intrinsic HIF1α pathway as a major functional mechanism in ICBs." (PMID 39477954, 2024). "This pathway contributes to elevated levels of HIF-1α protein in hypoxic cells, thereby positively regulating the transcriptional activation of HIF-1 target genes and vascular endothelial growth factor (VEGF) in tumor cells during hypoxia." (PMID 38539163, 2024). "The stabilization of Hif-1α in the absence of Sirt-3 has been described previously and is mostly considered in the context of the tumor microenvironment and the Warburg effect." (PMID 38612678, 2024). "Moreover, HIF-1α upregulates the expression of CD39 and CD73 on the tumor cells, contributing to the accumulation of adenosine in the TME." (PMID 39650654, 2024). "Hence, in GBM, there is an increasing body of data on HIF-1, its subunit HIF-1α, and VEGF expression regarding their relationship and possible involvement in prognosis and tumor progression." (PMID 39055895, 2024). "HIF1α can transcriptionally activate several proangiogenic factors, such as VEGFA, which promotes the formation of new blood vessels to enhance oxygen delivery to tumor cells and facilitate their growth." (PMID 39532855, 2024). "Furthermore, HIF-1α collaborates with other factors like TGF-β2 to activate genes such as GLI2, which enhance intrinsic tumor resistance to chemotherapeutic drugs." (PMID 38396737, 2024). "S1C), nine populations were identified as tumor cells, two corresponded to neuroglia (astrocytes and other CNS cells), three to nonmyeloid immune populations (lymphocytes and a HIF1a+ immune population), and one to vascular cells." (PMID 38758780, 2024). "Pearson correlation analysis showed a negative correlation between HIF‐1α and H3K27me3 in 81 tumor tissues, which is consistent with our in vitro results." (PMID 38072662, 2024).